SOD2 (superoxide dismutase 2)
Diseases named in the same sentence as SOD2 in open-access papers (continued):
Sharing a sentence is not in itself a finding about the gene and the disease.
Hyperglycemia (95 papers, 2007 to 2025). An increased concentration of glucose in the blood. "For instance, interventions aimed at restoring the function of antioxidant enzymes, such as superoxide dismutase 2 (SOD2), have shown promise in protecting retinal cells from the long-term damage caused by hyperglycemia-induced metabolic memory." (PMID 40589740, 2025). "Our results indicate that hyperglycemia induces SOD2 expression through decreased association of Egr1 on the SOD2 promoter." (PMID 31685635, 2019). "In the present study, we demonstrated that hyperglycemia caused reduction of renal mitochondria SOD2 and enhancement of UCP2, then reduced ATP production by the mitochondria." (PMID 31406124, 2019). "Elevated levels of Sod2 have been shown to be associated with a strain of rat that is resistant to hyperglycemia-induced embryonic malformations." (PMID 26887929, 2016). "The correction of respiratory chain deficiency by SOD2 suggests that oxidative stress impairs the OXPHOS system in MSCs experiencing hyperglycemia." (PMID 26652025, 2015). "During hyperglycemia, excess glucose levels induce over-production of ROS in the mitochondria, which subsequently causes depletion of SOD2 and leads to cellular injury." (PMID 20976160, 2010). "Because SOD2 is exclusively localized to the mitochondria of SOD2 transgenic mice, our data is indicative of the critical role that mitochondrial oxidative stress plays during hyperglycemia as mitochondrial oxidative stress has been implicated in diabetic associated pathologies." (PMID 20976160, 2010). "Prolonged exposure to hyperglycemia has been shown to lead to epigenetic changes that downregulate the expression of SOD2 in retinal cells, resulting in the accumulation of oxidative damage that persists even after blood glucose levels are controlled." (PMID 40589740, 2025). "Superoxide dismutase (Sod1, Sod2) and catalase (Cat) are potent antioxidant enzymes and regulate the levels of reactive oxygen species (ROS) generated through hyperglycemia." (PMID 37110174, 2023). "Researchers also found that hyperglycemia led to histone H3 on lysine 9 di-methylation (H3K9me2) combination more in Sod2 promoter region in autistic mice of maternal diabetes." (PMID 37255932, 2023). "In this study, SOD2 was overexpressed by SOD2 lentivirus infection to diminish ROS generation and subsequently reverse hyperglycemia/oxidative stress-mediated epigenetic changes on the RORA promoter." (PMID 35027651, 2022). "In the context of hyperglycemia, NF-κB stimulation regulated by H3K4 and H3K20 modifications is strongly associated with modulation of the transcription of SOD2 and iNOS, which generates ROS in diabetic retinopathy." (PMID 35340204, 2022). "Hyperglycemia can cause oxidative stress to produce many ROS, reduce the expression of anti-oxidant enzymes such as CuZnSOD (SOD1) and MnSOD (SOD2), increase AGEs, activate protein kinase C (PKC) dependent ERK signaling pathway, and cause liver dysfunction." (PMID 35845802, 2022). "SIL promotes the expression of SIRT1, FoxO1, CAT, GPX1 and SOD2 of hyperglycemia Intervention of MC3T3-E1 by reducing intracellular ROS levels and restoring the activity and function of MC3T3-E1, similar to those from some researches." (PMID 36057883, 2022). "Prolonged hyperglycemia is responsible for inducing oxidative stress as evident by increased ROS production and decreased antioxidant proteins, including SOD2, HO-1 and NQO145,46." (PMID 33479232, 2021). "The results showed that both SOD2 (↑SOD2) and Egr1 (↑Egr1) lentivirus completely restored hyperglycemia-induced H3K9me2 modification and SOD2 suppression." (PMID 31685635, 2019). "In this study, we demonstrated that transient hyperglycemia exposure induces maintained ROS generation, resulting in suppression of ERβ and SOD2 and forming a positive feed-forward loop for ROS generation in subsequent normoglycemia." (PMID 31396159, 2019).
Hyperglycemia (continued). "We found that transient hyperglycemia exposure induces persistent oxidative stress with maintained suppression of ERβ, SOD2, and the VEGF (vascular endothelial growth factor) signaling pathway after switching to normoglycemia." (PMID 31396159, 2019). "Our results demonstrated that downregulation of renal mitochondria PRR via PRR shRNA delivery efficiently blocked hyperglycemia-induced dysfunction of mitochondria by reversing SOD2 levels, inhibiting UCP2 protein levels, and increasing ATP synthesis." (PMID 31406124, 2019). "We conclude that maternal diabetes induces autism-like behavior through hyperglycemia-mediated persistent oxidative stress and SOD2 suppression." (PMID 31685635, 2019). "The results of in vitro study showed that transient hyperglycemia induces persistent reactive oxygen species (ROS) generation with suppressed superoxide dismutase 2 (SOD2) expression." (PMID 31685635, 2019). "Further investigation showed that hyperglycemia-induced SOD2 suppression is due to persistent oxidative stress-mediated histone methylation and the subsequent decreased association of Egr1 on the SOD2 promoter." (PMID 31685635, 2019). "Our results indicate that maternal diabetes-induced oxidative stress and mitochondrial dysfunction is due to hyperglycemia-induced SOD2 suppression." (PMID 31685635, 2019). "Hyperglycemia induces persistent oxidative stress and superoxide dismutase 2 (SOD2) suppression in neurons." (PMID 31685635, 2019). "Taken altogether, our results show that hyperglycemia-induced ROS generation suppresses ERβ expression and subsequently results in SOD2 suppression with further elevated ROS generation." (PMID 31396159, 2019). "In this study, we demonstrated that transient hyperglycemia induces persistent oxidative stress with maintained SOD2 suppression during subsequent normoglycemia." (PMID 31685635, 2019). "Our results indicate that expression of either ERβ or SOD2, or ERβ agonist treatment, diminishes hyperglycemia-induced persistent ROS generation." (PMID 31396159, 2019). "On the contrary, hyperglycemia-induced persistent elevated ROS generation was completely diminished after infection of either SOD2 lentivirus (↑SOD2) or Egr1 lentivirus (↑Egr1)." (PMID 31685635, 2019). "Our results indicate that hyperglycemia-induced SOD2 suppression in neurons is due to hyperglycemia-induced H3K9me2 histone methylation and the subsequent dissociation of Egr1 on the SOD2 promoter." (PMID 31685635, 2019). "Our results show that transient hyperglycemia exposure results in persistent ROS overgeneration after the switch to normoglycemia, along with suppressed expression of ERβ, SOD2, and the VEGF signaling pathway." (PMID 31396159, 2019). "We found that transient hyperglycemia exposure induces persistent SOD2 suppression during subsequent normoglycemia." (PMID 31685635, 2019). "Further investigation showed that hyperglycemia-induced oxidative stress down-regulates ERβ expression, and subsequently suppresses SOD2 expression with a positive-feed forward loop to maintain elevated ROS generation even in subsequent normoglycemia." (PMID 31396159, 2019). "The results showed that both shEHMT1 and BIX-01294 completely restored hyperglycemia-induced decreased SOD2 reporter activity and enzyme activity." (PMID 31685635, 2019). "Transient hyperglycemia exposure induces ROS generation and suppresses ERβ expression, subsequently resulting in SOD2 suppression with additional elevated ROS generation." (PMID 31396159, 2019). "We also found that hyperglycemia-induced SOD2 suppression is due to oxidative stress-mediated histone methylation with H3K9me2 and the subsequently decreased binding ability of Egr1 on the SOD2 promoter." (PMID 31685635, 2019). "We found that transient hyperglycemia exposure induces persistent oxidative stress and superoxide dismutase 2 (SOD2) suppression in in vitro cell experiments." (PMID 31685635, 2019).
Hyperglycemia (continued). "We measured hyperglycemia-induced histone modification H3K9me2 on the SOD2 promoter and SOD2 mRNA expression." (PMID 31685635, 2019). "Recently, we observed impaired expression of manganese-superoxide dismutase 2 (SOD2) in HUVECs exposed to a GV model, suggesting the damaging effects of hyperglycaemia on the antioxidant defence system." (PMID 30037352, 2018). "Sustained hyperglycemia induces the over-production of reactive oxygen species in the mitochondria, mitochondrial antioxidant enzymes such as superoxide dismutase 2 are depleted, and neuronal injury results." (PMID 29017498, 2017). "When excess mitochondrial superoxide is reduced using mitochondria specific SOD2 gene upregulation the hyperglycemia induced effects are abrogated including reduction of cellular inflammation." (PMID 26652025, 2015). "The percentage of positive SOD2 and uPA staining cancer cells were significantly higher in the hyperglycemia group than in the euglycemia group." (PMID 26439801, 2015). "The SOD2 and uPA stainings in the cytoplasm of the cancer cells was significantly stronger in the hyperglycemia group than in the euglycemia group, indicating that hyperglycemia is able to increase the expression of SOD2 and uPA protein levels." (PMID 26439801, 2015). "Taken together, our results demonstrate that hyperglycemia enhances cell invasive ability through the SOD2/H2O2/MAPK axis in human pancreatic cancer." (PMID 26439801, 2015). "Silencing of LSD1 ameliorates the epigenetic alterations due to hyperglycemia and prevents the downregulation of sod2 expression." (PMID 25165577, 2014). "The sod2 plays a protective role to prevent hyperglycemia-induced damage of mitochondria DNA (mtDNA) in DR." (PMID 25165577, 2014). "We observe that the increased phosphorylation of p38 MAPK in WT-STZ mice is ameliorated in SOD2-overexpressing mice despite the presence of hyperglycemia." (PMID 20976160, 2010). "Upon overexpression of SOD2, mitochondrial antioxidant enzyme, hyperglycemia-induced oxidative stress-related axonal transport deficits recover." (PMID 20976160, 2010). "Recently, Munusamy and Mac-Millan-Crow reported that overexpression of SOD2 prevented early stage hyperglycemia-induced mitochondrial injury in normal renal rat proximal tubular cells." (PMID 20976160, 2010). "In this study, we utilized two different animal models: (i) STZ-induced hyperglycemia mice and (ii) a heterozygotic SOD2 overexpressing STZ-treated hyperglycemia mice." (PMID 20976160, 2010). "Taken together, the data indicate that phosphorylated p38 MAPK levels increase in association with ROS in hyperglycemic mice with increased oxidative stress and return to wildtype levels in SOD2-STZ mice that have reduced superoxide load despite hyperglycemia." (PMID 20976160, 2010). "Whereas hyperglycemia-induced oxidative stress damages peripheral neurons, overexpression of SOD2 reduces the superoxide load and prevents hyperglycemia-induced cellular injury in dorsal root ganglia (DRG) cultures." (PMID 20976160, 2010). "To determine if axonal transport deficits were associated with hyperglycemia-induced oxidative stress, we measured axonal transport rates with MEMRI in STZ-treated SOD2 overexpressing mice (SOD2-STZ)." (PMID 20976160, 2010). "Additionally, in an in vivo model of streptozotocin‐induced hyperglycemia and diabetes type I in rats, CV showed beneficial effects on diabetic cardiomyopathy and increased protein expression of SOD2, SOD1, and catalase in heart and skeletal muscle." (PMID 39924769, 2025). "Furthermore, GLP-1R agonism can reduce gene transcription of nuclear factor kappa-B (NF-κB) and superoxide dismutase 2 (SOD2) by reversing the hyperglycaemia-induced DNA demethylation." (PMID 39200816, 2024).
Hyperglycemia (continued). "Interestingly, C. papaya treatment in hyperglycaemia-induced HepG2 cells led to a decrease in SOD2 protein expression in HGL500 (0.2755 ± 0.02706 RBD, p = 0.0198) and HGL1000 (0.3486 ± 0.004017 RBD, p = 0.0672) by 0.53 and 0.83, respectively." (PMID 39458491, 2024). "We have recently reported that maternal diabetes induces ALB through hyperglycemia‐mediated persistent oxidative stress and Sod2 mRNA suppression, indicating that SOD2 may play an important role in maternal diabetes–mediated ALB and GI dysfunction." (PMID 35220596, 2022). "Furthermore, we evaluated the possible effect of hyperglycemia and SOD2 expression on H4 methylation and histone acetylation on the CLDN1 (online only) and ZO1 (online only) promoters; neither showed any changes." (PMID 35220596, 2022). "In this study, we show that transient hyperglycemia-mediated oxidative stress suppresses the expression of RORA, CYP19A1, and SOD2; prenatal RORA deficiency mimics maternal diabetes-mediated ALB, and postnatal RORA manipulation in the amygdala modulates maternal diabetes-mediated ALB in offspring." (PMID 35027651, 2022). "This indicates that hyperglycemia-induced persistent oxidative stress and epigenetic changes on the SOD2 promoter may be the potential driving force for damage in neurons and subsequently contribute to ASD development." (PMID 31685635, 2019). "We conclude that maternal diabetes may induce autism-like behavior, in part through hyperglycemia-mediated persistent oxidative stress and SOD2 suppression." (PMID 31685635, 2019). "Our study showed that transient hyperglycemia induces persistent SOD2 suppression in cells." (PMID 31685635, 2019). "Our results indicate that hyperglycemia-induced persistent epigenetic changes with H3K9me2 and subsequent SOD2 suppression may be due to hyperglycemia-induced persistent oxidative stress." (PMID 31685635, 2019). "We investigated the potential molecular mechanism for hyperglycemia-induced SOD2 suppression." (PMID 31685635, 2019). "The possible mechanism is that hyperglycemia can increase the concentration of H2O2 by up-regulating the expression of manganese superoxide dismutase (SOD2), and then activate the extracellular signal-regulated kinase (ERK) and protein 38 mitogen-activated protein kinases (p38 MAPK) pathways." (PMID 31337431, 2019). "We first evaluated the effect of hyperglycemia on the gene expression of SOD2 and ERβ." (PMID 31685635, 2019). "Also, hyperglycemia increases acetyl H3K9, H4K20me3 via NF-κB controlled genomic sequences encoding retinal Sod2, SUV420h2, and concurrently enhances the interactions between NF-κβ subunit of p65 to H4K20me3 and acetyl H3K9." (PMID 30233418, 2018). "In addition, to further demonstrate the role of miR-21 in Ox-S, we measured miR-21 and SOD2 levels during treatment with a pro-oxidant agent, hydrogen peroxide, demonstrating the sensitivity of miR-21 expression in an oxidative context, hyperglycaemia-induced." (PMID 30037352, 2018). "Here we show that hyperglycemia increases the hydrogen peroxide (H2O2) concentration through up-regulation of manganese superoxide dismutase (SOD2) expression, which further activates the ERK and p38 MAPK pathways, as well as the transcription factors NF-κB and AP-1, in a time-dependent manner." (PMID 26439801, 2015). "In addition, hyperglycemia is correlated with increased expression levels of SOD2 and uPA in the tissue specimens obtained from PC patients." (PMID 26439801, 2015). "Furthermore, the potential driving force for hyperglycemia memory has been identified to be hyperglycemia-mediated ROS generation and oxidative stress, and overexpression of SOD2 could restore this." (PMID 35027651, 2022).
Hyperglycemia (continued). "The valine-to-alanine substitution induces the conformational changes with a less efficient transport of SOD2 into the mitochondrial matrix and, finally, lowers the ability to neutralize the superoxide radicals, which are largely produced in the mitochondria of the patients with hyperglycemia." (PMID 34746177, 2021). "We then mutated these potential binding motifs in the SOD2 full length (pSOD2-2000) reporter construct, and the reporter assay showed that hyperglycemia-induced SOD2 suppression did not occur on the Egr1 binding motif mutation located at −262 and −132, respectively." (PMID 31685635, 2019). "Epigenetic alterations induced by hyperglycemia, including increased methylation at H4K20, acetylation at H3K9, and LSD1-mediated demethylation at H3K4, affect the promoter and enhancer regions of SOD2, resulting in its downregulation." (PMID 40589740, 2025). "Our results showed that intracellular oxidative stress in hyperglycemia was overexpressed, while FoxO1, SIRT1, GPX1, and SOD2 were downregulated." (PMID 36057883, 2022). "Our results suggest that transient hyperglycemia triggers persistent RORA suppression during subsequent normoglycemia and that the expression of CYP19A1 and SOD2 is regulated by RORA." (PMID 35027651, 2022). "In summary, our research results confirm that hyperglycemia impaired the activity and function of MC3T3-E1 and inhibits bone formation by up-regulating intracellular ROS levels through inhibition of SIRT1/SOD2 signaling pathway." (PMID 36057883, 2022). "In vitro, using human colon stem cells, we show that transient hyperglycemia induces persistent suppression of CLDN1 and ZO1 through epigenetic modifications, and that SOD2 expression reverses, while short‐hairpin (sh)SOD2 expression mimics, this effect." (PMID 35220596, 2022). "We found that two anti-oxidant proteins (SOD2 and CAT) were decreased in 16-week-old diabetic mice, along with severe hyperglycemia and low insulin levels." (PMID 34249264, 2021). "Another study showed that hyperglycemia increased the binding of the histone demethylase lysine-specific demethylase-1 (LSD1) and Sp1 at Sod2, and decreased monomethyl H3K4 and dimethyl H3K4." (PMID 33537003, 2020). "Hyperglycemia reduces monomethyl histone H3 at lysine 4 (H3K4me1) and dimethyl H3 K4 (H3K4me2), while it increases the binding of LSD1 to sod2, leading to a decrement of sod2 expression." (PMID 25165577, 2014). "Moreover, hyperglycemia reduced H3K4me1 and -me2 and increased the binding of Lysine-specific demethylase 1 (LSD1) and Sp1 at the Sod2 gene." (PMID 36732760, 2023). "Transcript levels of Nqo1 and Sod2 were significantly elevated in STZ-diabetic mice following acute hypoglycaemia (STZ-LH vs WT-EE; p<0.05 for both genes), and the levels of Sod2 were further increased (>fivefold) in chronic hyperglycaemia." (PMID 37015997, 2023). "Studies conducted on male C57BL/6 mice in whom hyperglycemia was induced with streptozotocin showed an increase in MDA and a decrease in total antioxidant capacity (TAC), SOD total, SOD2 (Mn-dependent SOD), and the GSH/GSSG (glutathione disulfide) ratio in the endothelium." (PMID 34836227, 2021). "Compared with the LECs in normal mice, there were increased expressions of the oxidative stress markers of SOD2 and CAT in the cells subjected to hyperglycemia in the first 2 months, but an obvious reduction at 4 months, which was in line with a previous study about the corneas of diabetic mice." (PMID 32186721, 2020). "Our results indicate that SOD2 expression is regulated by ERβ, and ERβ overexpression by lentivirus or ERβ activation by ERβ agonist DPN upregulates SOD2 expression and subsequently diminishes hyperglycemia-induced persistent ROS generation." (PMID 31396159, 2019). "We first evaluated histone H4 methylation on the SOD2 promoter and found that hyperglycemia did not have any effect on histone H4 methylation." (PMID 31685635, 2019).